LEP (leptin)
Diseases named in the same sentence as LEP in open-access papers (continued):
Sharing a sentence is not in itself a finding about the gene and the disease.
Obesity (continued). "However, hypothalamic leptin sensitivity is known to be impaired despite elevated circulating leptin concentrations under conditions of obesity, a phenomenon regarded as leptin resistance." (PMID 32670063, 2020). "Sh2b1-null mice develop severe leptin resistance, obesity, and type 2 diabetes." (PMID 32251290, 2020). "Leptin is an adipocyte derived hormone secreted from adipocyte and plays an important role in amelioration of complications and pathogenesis of obesity as it acts on the hypothalamus to control appetite, food intake, energy metabolism, and sympathetic nervous system outflow." (PMID 32197395, 2020). "The relationship between leptin and food intake changes with obesity." (PMID 32160920, 2020). "Patients with obesity have hyperleptinemia due to the development of leptin resistance." (PMID 32130282, 2020). "Since leptin acts as a proinflammatory adipokine, the hyperleptinemia may contribute to the chronic inflammatory state of obesity." (PMID 32824322, 2020). "Additionally, mice with diet-induced obesity with lncOb knockout exhibit increased fat mass, with reduced plasma leptin levels." (PMID 32561739, 2020). "Importantly, appetite homeostasis is known to be altered in obesity due at least in part to hypothalamic inflammation and reactive gliosis that results in functional impairment of anorexigenic neurons and central leptin and insulin resistance." (PMID 32604889, 2020). "Therefore, elafin induces leptin expression and reduces food consumption, obesity, and hyperglycemia via serum exosomal miR181b-5p and miR219-5p." (PMID 32733043, 2020). "Furthermore, developing diet-induced obesity often resulted from the failure of leptin mediated signaling in POMC and AgRP neurons in ARC." (PMID 32272767, 2020). "There is a strong link between asthma and obesity regarding serum levels of leptin and adiponectin." (PMID 32143340, 2020). "Signaling pathways affected by gene dysregulation in the atopic group included angiopoietin signaling, epidermal growth factor signaling, AMP-activated protein kinase signaling, retinoid X receptor (RXR)/farnesoid X receptor (FXR) signaling, and leptin signaling in obesity." (PMID 33178726, 2020). "Obesity is characterized by hyperleptinemia due to the development of leptin resistance." (PMID 32374776, 2020). "The importance of leptin is clear from the finding that genetically caused lack of leptin results in severe obesity that can be reversed by leptin treatment in both experimental animals and humans." (PMID 32510046, 2020). "Nevertheless, although the association between neonatal leptinemia and childhood growth and adiposity (e.g., weight gain, BMI, and/or obesity) has been previously reported, the impacts of altered neonatal leptin levels on fat distribution during childhood still need to be clearly defined." (PMID 31947745, 2020). "However, abnormal or excessive fat accumulation in the context of obesity can lead to increased leptin levels, producing a phenomenon called “leptin resistance”, in which leptin signaling is attenuated." (PMID 32839413, 2020). "Another characteristic of obesity is an imbalance of adipokines, including leptin." (PMID 33256096, 2020). "Obesity might influence serum kisspeptin levels during the progression of puberty due to the disturbance of hypothalamic kisspeptin by inflammatory cytokines, leptin, insulin resistance, and elevated estrogen secondary to obesity." (PMID 33224197, 2020). "Obesity induced by high unsaturated-fat diet in rat has improved vascular reactivity to leptin and does not generate endothelial dysfunction, possibly due to the increase of vascular sensitivity to leptin and leptin-induced NO bioavailability." (PMID 33062134, 2020). "Obesity-associated inflammation is characterized by elevated serum levels of pro-inflammatory cytokines such as interleukin-1 (IL-1), IL-6, and tumor necrosis factor alpha (TNF-α), as well as altered levels of adipokines such as leptin and adiponectin." (PMID 32295649, 2020).
Obesity (continued). "We sought to quantify the effects of sleeve gastrectomy on leptin, adiponectin and LAR in adults with severe obesity, and to assess whether the magnitude of weight loss after surgery influenced the change in LAR." (PMID 33004989, 2020). "A central leptin resistance in obesity is widely accepted; therefore, a peripheral leptin resistance with an abrogated JAK/STAT signaling pathway is likely and would explain the reduced biological activity after leptin challenge in NK cells of obese individuals." (PMID 32231659, 2020). "Therefore, these evidences and current findings together suggest that MyD88 signaling in astrocytes is important in leptin resistance caused by HFD-induced inflammation and obesity pathogenesis." (PMID 32560726, 2020). "Leptin is a marker of obesity and promotes breast carcinogenesis through several mechanisms." (PMID 33019728, 2020). "Interestingly, most obese individuals have high levels of circulating leptin, which is seemingly inconsistent with obesity, indicating a state of leptin resistance." (PMID 32013093, 2020). "Animal models have indicated that hyperthyropinemia seen with obesity may be driven by the enhanced leptin-mediated production of pro-thyrotropin releasing hormone (TRH) or due to impaired feedback due to decreased number of T3 receptors in the hypothalamus." (PMID 32569304, 2020). "This notion is supported by previous reports demonstrating that ERα signaling mediates the growth of breast cancer cells under various pathological conditions, including obesity and crucially contributes to inflammasomes activation and tumor growth induced by leptin, another well-known adipokine." (PMID 32155890, 2020). "Leptin is considered a potential marker of obesity-related complications." (PMID 32443588, 2020). "Children with obesity tend to have higher circulating blood insulin and leptin levels and may develop resistance to the actions of insulin and leptin." (PMID 33266497, 2020). "In addition, RPA can reduce the serum TG, malondialdehyde, leptin and TNF-α levels caused by ovariectomies, so as to improve the lipid metabolism disorder and inhibit obesity." (PMID 32489401, 2020). "Specifically, peripheral blockade and hepatic deletion/overexpression of CB1R modulate the expression levels of the sOb-R isoform in hepatocytes and its subsequent release into the circulation, reversing the CB1R-mediated decrease in sOb-R levels and hepatic leptin resistance during obesity." (PMID 33210603, 2020). "However, the scientific excitement about leptin discovery faded when it was demonstrated that plasma leptin levels were increased in obesity and metabolic diseases, defining a state of leptin resistance." (PMID 32756352, 2020). "Also, we reported this mouse model displayed obesity and metabolic syndrome, mediated by leptin signaling disruption in the hypothalamus, upon normal chow diet administration." (PMID 31937343, 2020). "In vivo and in vitro data indicate that primary cilium dysfunction may promote adipogenesis, thus contributing to the development of dysregulation of energy homeostasis, leptin resistance, and obesity." (PMID 33139642, 2020). "Anyhow, reduced leptin level may be considered as a beneficial effect because leptin has pro-inflammatory effects and contributes to the development of co-morbidities of obesity." (PMID 32379797, 2020). "Yet, several differences exist between the genetic obesity and diet-induced obesity models, which typically are characterized by hyperleptinemia, and leptin still might play a critical role in human obesity-promoted PDAC." (PMID 32709161, 2020). "Diet-induced obesity resulted in upregulation of the plasma leptin concentration." (PMID 32104148, 2020). "Many mutations in the LEP and LEPR genes have a major influence on metabolism, leading to obesity." (PMID 32982666, 2020). "It is well known that all through obesity, changes in adipokine (adiponectin, leptin, etc.)levels may occur." (PMID 32685140, 2020).
Obesity (continued). "The effects of both leptin and adiponectin in obesity may be mediated by AMPK since their receptor binding can activate AMPK, which inactivates acetyl-CoA carboxylase (ACC1)." (PMID 33142995, 2020). "LEP in the serum is a commonly highlighted adipokine in obesity-related OA." (PMID 32709032, 2020). "Besides, rats harboring a deletion of the 14th amino acid Ile, and mice carrying a substitution of the 145th amino acid from Val to Glu in the leptin protein also show signs of obesity, hyperglycemia, hyperinsulinemia, and insulin resistance." (PMID 32585823, 2020). "However, most cases of obesity are characterized by hyperleptinemia, indicating that obesity is a leptin-resistant state, where leptin signaling is impaired." (PMID 33210603, 2020). "It is tempting to speculate that, during climacterium, the loss of ovarian hormones may induce an early, moderate but significant increase in leptin levels, while obesity further increases leptin levels chronically over time." (PMID 32555994, 2020). "In order to understand whether HFD alone and in combination with 13 cRA has an effect on obesity and weight control, we investigated leptin and adiponectin levels and lipid parameters (triglyceride [TG] and total cholesterol levels [TC], HDL-c, LDL-c)." (PMID 32947606, 2020). "Leptin is assumed to be the main contributor to inflammatory and pain-related effects in obesity." (PMID 33396484, 2020). "In addition, other products of adipose tissue such as, leptin, are thought to provide an important link between obesity, insulin resistance and related inflammatory disorders." (PMID 32824322, 2020). "Moreover, leptin, a hormone secreted by adipocytes was increased in obesity as compared to eutrophic adolescents, in both sexes." (PMID 33644105, 2020). "We analyzed whether the less pronounced effects of leptin in the thermoneutral mice were related to the obesity of these mice and their corresponding leptin levels." (PMID 31743040, 2020). "Besides, a marked increase of leptin was found in obese individuals, particularly in those with the coexistence of psoriasis and obesity." (PMID 33008429, 2020). "A question remains as to which of the strains of the ob/ob displays the “real” phenotype of leptin-deficiency and whether BAT defects in ob/ob mice contribute in any way to their obesity." (PMID 31774114, 2020). "Further supporting the notion that leptin may reduce CD8+ T cell anti-tumor function in the context of obesity, a recent study found that leptin contributes to CD8+ tumor-infiltrating lymphocyte (TIL) dysfunction in a spontaneous breast cancer model." (PMID 33170123, 2020). "Increased circulating levels of the adipokine leptin with diet-induced obesity contribute to the observed dysfunction in CD8+ T cells in the context of cancer, as leptin receptor-deficient T cells mount a more effective anti-tumor response after adoptive transfer into HFD-fed recipients." (PMID 33170123, 2020). "Two obesity-related genes, such as LEP and NEGR1, may play a substantial role in the occurrence of two types of cancers (BRCA and BLCA)." (PMID 33299884, 2020). "The current data also points to the DVC astrocytes as a site of leptin dysfunction in obesity." (PMID 32152264, 2020). "Moreover, the role of fat around the upper airways and pharynx, as well as hormonal changes of adiponectin, leptin, ghrelin, and even growth hormones, has been examined in several studies, addressing obesity and OSA mechanisms." (PMID 33101432, 2020). "However, in obesity, despite elevated leptin concentrations, the effect of leptin is reduced due to leptin resistance." (PMID 32927680, 2020). "The impaired insulin signaling pathway may, therefore, as with leptin, contribute to the development of neuropsychiatric symptoms in the context of obesity." (PMID 32545890, 2020). "Independent of leptin-deficient obesity and dietary obesity, a course of 8-week IL-4 supplementation improved obesity and impairment in Akt, STAT3, and STAT6 signaling." (PMID 32585823, 2020).
Obesity (continued). "Restricting food intake to the resting phase worsened fasting and postprandial glucose concentrations, blood pressure, and lipid concentrations in humans, and induced leptin resistance that contributes to the development of obesity and metabolic disorders in mice." (PMID 32283715, 2020). "Moreover, high serum leptin concentrations coexist with leptin receptors resistance, and these disturbances are related to obesity." (PMID 33008429, 2020). "Obesity decreased sensitivity to leptin, developed leptin resistance." (PMID 32042300, 2020). "Leptin has an essential influence on the anti-obesity effects of PNS." (PMID 33042284, 2020). "There was no observed association between markers of obesity (BMI, insulin, leptin, and CRP), serum 25-OH vitamin D levels and estradiol or estrone levels." (PMID 32566743, 2020). "Thus, researchers will conduct more detailed studies on the anti-obesity effects of nutritional factors targeting the gut microbiota on the participation of leptin in browning." (PMID 33042284, 2020). "The discovery of leptin was a turning point for two principle reasons: on one hand, it generated promising expectations for the treatment of the obesity, and on the other, it changed the classical concept that white adipose tissue was simply an inert storage organ." (PMID 32839413, 2020). "Increased leptin level could be secondary to autonomic imbalance or obesity-related leptin resistance." (PMID 33076921, 2020). "In this context, several micro- and macro-nutrients and bioactive food components might have the ability to increase leptin sensitivity and to reverse leptin resistance in obesity and GDM." (PMID 32630697, 2020). "Yet, some evidence suggested that leptin may exert a regulatory effect in GLP-1 secretion and that impairment of leptin regulation associated with obesity may also be associated with impairment of GLP-1 regulation." (PMID 33324496, 2020). "Leptin and adiponectin play important roles in obesity‐related inflammation and comorbidities." (PMID 31880032, 2020). "Decreased SHBG is the predominant factor in men with mild obesity, whereas suppression of the hypothalamic-pituitary-testicular axis by inflammatory cytokines and leptin might be mainly responsible for low testosterone in men with severe obesity." (PMID 32535783, 2020). "This implies that, after prolonged HFD feeding, leptin resistance is the consequence of the obese state and not the cause of obesity development." (PMID 33105762, 2020). "The alteration of the leptin level was particularly marked in class III obesity." (PMID 32316563, 2020). "As obesity develops, plasma leptin levels are known to increase." (PMID 38304556, 2020). "Kisspeptin level may be affected by other metabolic and hormonal disorders that accompany obesity, for instance leptin level." (PMID 32411228, 2020). "Chronic low grade inflammation in obesity that may contribute to muscle wasting is regulated in part by adiponectin, leptin, and insulin controlling various inflammatory and anti-inflammatory processes." (PMID 33117276, 2020). "Furthermore, blood leptin and glucose level of high-fat diet-induced obesity mice were all lowered, showing berberine to be a potential natural that did not produce any physiological changes in normal diet mice." (PMID 33415147, 2020). "Although their functional outcomes remain largely unknown, single nucleotide polymorphisms (SNPs) in the fat mass and obesity-associated gene (FTO) may interact with adipokines, especially leptin and adiponectin, to modify the risk of colorectal cancer." (PMID 32053666, 2020). "Commiphora myrrha extract normalized serum leptin levels through different possible pathways such as increasing UCP1 expression in brown adipose tissue, which subsequently increased energy expenditure and reduced obesity development which reduced leptin synthesis and secretion by adipocytes." (PMID 32197395, 2020).
Obesity (continued). "Leptin-deficient ob/ob mice are characterized not only by hyperphagia and obesity but also mild hypothermia; such mice will not survive a prolonged cold exposure." (PMID 32178438, 2020). "In the other way around obesity has been found to be an important risk factor for the severity of some viral infections such as severe acute respiratory syndrome coronavirus 2 (SARS-CoV-2) and leptin has also been proposed as the possible link." (PMID 32824322, 2020). "Obesity leads to an increase in the adipokine leptin and a decrease in adiponectin." (PMID 32630445, 2020). "Given that JAK2 plays a critical role in brown adipose tissue function and diet-induced thermogenesis in HFD mice, JAK2 signaling between leptin and IFNγ may play a critical role in obesity-related inflammation and metabolic disorders." (PMID 33379198, 2020). "Unlike leptin and insulin, obesity does not seem to cause peripheral resistance to PYY, suggesting that the observed increases in older adults are likely to exert anorectic effects." (PMID 31432431, 2020). "Interestingly, EE inhibits mammary tumor growth rate with intact leptin signaling in diet-induced obesity models." (PMID 33117814, 2020). "As MetS describes a cluster of metabolic abnormalities, leptin may be a significant factor linking obesity, MetS, and CVD." (PMID 32517169, 2020). "Additionally, we found weak to moderate negative correlations between OB volume and BMI as well as other measures of metabolic health in obesity, such as body fat percentage, WHtR, leptin levels and insulin resistance." (PMID 33328935, 2020). "A study in mice evaluating obesity-promoted breast tumor growth showed that increased oxidation of fatty acids and reduced glycolysis, both enhanced by the leptin-PD-1-STAT3 axis in CD8+ TILs, promoted obesity-related breast tumorigenesis and contributed to resistance to immunotherapy." (PMID 33597950, 2020). "The two obesity-related hormones, adiponectin (regulates glucose and lipid metabolisms) and leptin (regulates food intake and energy expenditure), may have a small but significant effect to decrease body weight and fat mass." (PMID 32610476, 2020). "Leptin dysregulation occurs in the offspring with maternal HF diet and obesity." (PMID 32316577, 2020). "Obesity also affected cellular responses: PBMCs of the obese vaccinees had elevated interleukin 2 and interferon γ levels upon antigen stimulation, indicating a leptin-dependent proinflammatory TH1 polarization." (PMID 32528467, 2020). "Similar findings were described in B cells from obese patients, suggesting that the phenotype of inflammatory B cells in obesity may be mediated, at least in part, by leptin signaling." (PMID 33584724, 2020). "Leptin is associated with obesity: although it should reduce food intake and body weight, in obese patientsthe serum leptin levels are higher than in the lean individuals and do not manage reducing their food intake." (PMID 33375615, 2020). "In obesity and other inflammatory disorders, dietary flavonoids could inhibit inflammatory cytokine production, leptin secretion, insulin resistance, and improve immune responses." (PMID 33195370, 2020). "Both leptin and adiponectin, adipocyte-secreted cytokines, have a direct effect on endothelial function along with chemerin, a newly described adipokine involved in the obesity-inflammation cycle; its levels have been described to be higher in obesity." (PMID 32752277, 2020). "In addition, we also tested the spatial memory performance of leptin a (lepa) mutants which displayed an obesity phenotype." (PMID 32098080, 2020). "Obesity also preserves or enhances the central sympathoexcitatory response to leptin in males; while not yet investigated, because reproductive cycling becomes impaired, obesity may also further limit leptin-induced sympathoexcitation in females." (PMID 32160920, 2020).